SMARCAD1 (SNF2 related chromatin remodeling ATPase with DExD box 1)
Description:
Protein that possesses intrinsic ATP-dependent nucleosome-remodeling activity and is both required for DNA repair and heterochromatin organization. Combines the ATP-dependent ability to exchange histones, with the chaperone-like ATP-independent activity to deposit histones and assemble nucleosomes. Promotes DNA end resection of double-strand breaks (DSBs) following DNA damage: probably acts by weakening histone DNA interactions in nucleosomes flanking DSBs. Required for the restoration of heterochromatin organization after replication. Acts at replication sites to facilitate the maintenance of heterochromatin by directing H3 and H4 histones deacetylation, H3 'Lys-9' trimethylation (H3K9me3) and restoration of silencing.
Synonyms: KIAA1122; ETL1; DKFZP762K2015; ADERM; BASNS; HEL1; HPGDS-AS1; HRZ; TYS
Tractability: PROTAC: UniProt records ubiquitination sites on it; ubiquitination databases record sites on it; its protein half-life has been measured.
Gene: Protein-coding gene on chromosome 4 (94,207,605 to 94,291,293, forward strand). Ensembl gene ENSG00000163104.
Subcellular location: Nucleus; Chromosome
Subcellular location (Human Protein Atlas): Nucleoplasm
Gene Ontology:
Molecular function: ATP hydrolysis activity; ATP-dependent chromatin remodeler activity; ATP-dependent histone chaperone activity; DNA binding; protein binding; ATP binding; ubiquitin binding
Biological process: chromatin remodeling; chromosome separation; DNA double-strand break processing; regulation of DNA recombination; positive regulation of transcription by RNA polymerase II
Cellular component: chromosome; nuclear replication fork; nucleoplasm; nucleus; site of double-strand break; heterochromatin
Genetic constraint (gnomAD): Loss-of-function variants: 17 observed, 99.06 expected, observed/expected ratio (o/e) 0.17, 90% interval 0.12 to 0.26. The upper end of that interval is the gene's LOEUF score, 0.26, which puts it in group 1 of 6, group 1 being the genes least tolerant of losing a copy. Missense variants: 727 observed, 1,111.9 expected, observed/expected ratio (o/e) 0.65, 90% interval 0.61 to 0.69. Synonymous variants: 352 observed, 375.3 expected, observed/expected ratio (o/e) 0.94, 90% interval 0.86 to 1.02.
Homologues: Orthologues: chimpanzee SMARCAD1 (99% identical), macaque SMARCAD1 (99% identical), dog SMARCAD1 (97% identical), pig SMARCAD1 (97% identical), rabbit SMARCAD1 (96% identical), guinea pig SMARCAD1 (95% identical), rat Smarcad1 (93% identical), mouse Smarcad1 (92% identical), tropical clawed frog smarcad1 (64% identical), zebrafish smarcad1a (49% identical), zebrafish smarcad1b (46% identical), Drosophila melanogaster Etl1 (32% identical), and 1 more. Paralogues in human: SRCAP (25% identical), INO80 (24% identical), SMARCA4 (24% identical), SMARCA2 (24% identical), CHD1 (24% identical), CHD2 (24% identical), EP400 (23% identical), CHD9 (22% identical), HELLS (22% identical), CHD4 (22% identical), CHD7 (22% identical), CHD8 (22% identical), and 18 more.
Diseases named in the same sentence as SMARCAD1 in open-access papers:
SMARCAD1 is named in the same sentence as 29 diseases in open-access papers, as found by Europe PMC text mining. Sharing a sentence is not in itself a finding about the gene and the disease. The quoted sentences say what the papers report.
pancreatic cancer (3 papers, 2021 to 2022). "Reportedly, SMARCAD1 promotes the growth and metastasis of pancreatic cancer by activating the Wnt/β-catenin pathway." (PMID 34821374, 2022). "Meanwhile, some studies showed the SMARCAD1 was involved in the different cancer, like the breast cancer and pancreatic cancer." (PMID 35518785, 2022). "The previous study has indicated that SMARCAD1 is highly expressed in pancreatic cancer tissues and negatively correlated with survival time." (PMID 34315468, 2021). "On the contrary, in our study, we found that SMARCAD1 expressed lower in pancreatic cancer tissues than that in normal tissues, and significantly associated with unfavorable OS." (PMID 34315468, 2021). "Mechanistically, SMARCAD1 promotes pancreatic cancer cell growth and metastasis via activating Wnt/β-catenin-mediated EMT." (PMID 34315468, 2021). "However, lower protein expressions of SMARCAD1 was observed in pancreatic cancer tissues compared to normal tissues." (PMID 34315468, 2021). "Notably, the role of SMARCAD1 seems conflicting in pancreatic cancer." (PMID 34315468, 2021). "Results revealed that the mRNA levels of SMARCA3, SMARCA4, HELLS were significantly upregulated in patients with pancreatic cancer, while the mRNA levels of SMARCA2 and SMARCAD1 were downregulated." (PMID 34315468, 2021).
Basan Syndrome (2 papers, 2016 to 2023). "A heterozygous splicing mutation in a short isoform of human SMARCAD1 can cause adermatoglyphia (loss of fingerprints) and Basan syndrome, an ectodermal dysplasia with autosomal dominant inheritance and intra- and interfamilial variability." (PMID 26888216, 2016).
bladder cancer (2 papers, 2021). "However, the expression of SMARCAD1 in patients with bladder cancer was associated with an increased survival time." (PMID 34315468, 2021). "On the other hand, increasing the expression of SMARCAD1 and RTN4 decreases the incidence of death from bladder cancer." (PMID 34589136, 2021).
breast carcinoma (2 papers, 2021 to 2022). "On the one hand, knockdown of SMARCAD1 resulted in a significant decrease in breast cancer cell proliferation and colony formation, mainly through a potent inhibition of STAT3 phosphorylation." (PMID 34315468, 2021).
colitis (2 papers, 2020 to 2023). Inflammation of the colon. "We found that intestine epithelium-specific Smarcad1-KO protects the mice from DSS-induced colitis, reducing the response in terms of weight loss, disease activity index, MPO+ cell recruitment, and gene expression response." (PMID 32160911, 2020). "As we made these observations with an intestinal epithelium-specific deletion of Smarcad1, our observations underscore the importance of the intestinal epithelial tissue and innate immunity-linked processes in mediating a colitis response." (PMID 32160911, 2020). "A finer resolved hierarchical clustering was performed to detect genes with complete or near complete loss of expression changes on colitis in Smarcad1-KO." (PMID 32160911, 2020). "GO analysis of cluster 2, containing genes with complete loss of Smarcad1-dependent upregulation on colitis, yielded several enrichment terms." (PMID 32160911, 2020). "Deletion of SMARCAD1 in mice with colitis leads to increased expression of several genes, including those related to innate immune response." (PMID 38045758, 2023). "Mt1 that is significantly upregulated on Smarcad1 deletion plays an important role in the prevention of colonic mucosal inflammation in the dextran sodium sulfate (DSS)-induced mouse model of colitis." (PMID 32160911, 2020). "We identified several members of the gut microbiome that are responsible for a robust colitis response in a Smarcad1-dependent way." (PMID 32160911, 2020). "Consistent with a reduced colitis response, this occurred to a lesser extent in the Smarcad1-KO mice." (PMID 32160911, 2020). "We identify candidate members of the gut microbiome that elicit a Smarcad1-dependent colitis response, including members of the poorly understood TM7 phylum." (PMID 32160911, 2020). "Specific deletion of Smarcad1 in the mouse intestinal epithelium leads to colitis resistance and substantial changes in gene expression, including a striking increase of expression of several genes linked to innate immunity." (PMID 32160911, 2020). "Next, we repeated the colitis experiments with the microbiome-enriched control and Smarcad1-KO mice." (PMID 32160911, 2020). "On DSS treatment, the deletion of Smarcad1 leads to specific changes in gene expression consistent with the reduced colitis response." (PMID 32160911, 2020). "Most of these genes respond in the similar way to colitis on Smarcad1-KO." (PMID 32160911, 2020). "In addition to Smarcad1, we identify candidate bacterial species crucial for the phenotype severity of colitis, highlighting their potential as targets for pharmacological and probiotic treatment of intestinal inflammatory diseases." (PMID 32160911, 2020). "Our analysis shows that Smarcad1 deletion affects histone modifications in this tissue, modifying gene expression and intestinal epithelium-microbiome interactions, which, in turn, impinges on the colitis response in a DSS-induced mouse model." (PMID 32160911, 2020). "The GO analysis also highlights a potential role of Smarcad1 in the IL-17 pathway in colitis." (PMID 32160911, 2020). "However, a subset of genes shows incomplete upregulation on colitis induction in Smarcad1-KO mice." (PMID 32160911, 2020). "These are candidates for promoting colitis disease progression during the DSS treatment, requiring the presence of Smarcad1 in the intestinal epithelium." (PMID 32160911, 2020). "The transcriptome-based analysis of the colitis response illustrated the upregulation or shutdown of expression of many genes upon DSS treatment and shows that this transcriptional response was subdued for many genes in the intestine-specific Smarcad1-KO mice." (PMID 32160911, 2020).
non-small cell lung carcinoma (2 papers, 2022 to 2025). A group of at least three distinct histological types of lung cancer, including non-small cell squamous cell carcinoma, adenocarcinoma, and large cell carcinoma. "Then the relative gene and protein expressions of let-7f and its target genes, including HMGA2, ARID3B, SMARCAD1, and FZD3, were measured in lung tissues of Non-Small Cell Lung Cancer (NSCLC) patients and A549 cell line using quantitative real-time PCR and Western blotting." (PMID 35488374, 2022).
embryonal carcinoma (1 paper, 2009). A non-seminomatous malignant germ cell tumor characterized by the presence of large germ cells with abundant cytoplasm resembling epithelial cells, geographic necrosis, high mitotic activity, and pseudoglandular and pseudopapillary structures formation. "Smarcad1 preferentially binds to transcription start sites in embryonal carcinoma cells, which suggests that Smarcad1 is a gene specific transcription regulator rather than a ubiquitous chromatin modeling factor." (PMID 20019792, 2009).
liver cirrhosis (1 paper, 2023). "Obviously, the expressions of PPP1R12A, SP1 and SMARCAD1 in HCC tissues were higher than those in the liver cirrhosis tissues, which were opposite to the expression trend of KLF2 in HCC." (PMID 37386390, 2023).
lung carcinoma (1 paper, 2022). "In summary, the let-7f, as a major tumor suppressor regulatory factor, can exert its role in lung cancer via direct targeting genes such as HMGA2, SMARCAD-1, ARID-3, and FZD3 and can affect important processes, e.g. viability and proliferation of cancer cells." (PMID 35488374, 2022).
sclerotylosis (1 paper, 2021). "In Huriez syndrome, caused by skin-specific SMARCAD1 deficiency, patients feature a scleroatrophic phenotype, also seen in systemic sclerosis, which marks a strongly associated type I IFN activation disease." (PMID 34381458, 2021). "Mesenchymal stem cells of patients with systemic sclerosis reveal lower expression of SMARCAD1, suggesting Huriez syndrome and systemic sclerosis may share common pathways." (PMID 34381458, 2021).
tauopathy (1 paper, 2026). Neurodegenerative disorders involving deposition of abnormal tau protein isoforms (tau proteins) in neurons and glial cells in the brain. "Using forward and reverse genetic approaches in C. elegans, we identified smrd-1, the C. elegans homolog of SMARCAD1, as a potent modifier of tauopathy phenotypes in a transgenic model of tauopathy." (PMID 42204442, 2026).
cancer (6 papers, 2021 to 2025). A tumor composed of atypical neoplastic, often pleomorphic cells that invade other tissues. "However, other subunits such as SMARCE1 (BAF57), SMARCA2 (BRM) and SMARCAD1 (BAF60a) were implicated to promote cancers." (PMID 33670012, 2021). "SMARCAD1, a chromatin remodeler, is known as replication fork progressor, and SMARCAD1 dysregulation is also closely related to cancer development." (PMID 41641123, 2025). "Studies have pointed to a role for human SMARCAD1 in genomic instability during the past few years, which can lead to cell death or cancer development in higher eukaryotes." (PMID 34315468, 2021).
infection (6 papers, 2009 to 2025). The state of being infected such as from the introduction of a foreign agent such as serum, vaccine, antigenic substance or organism. "To explore further the potential association of HELLS/SMARCA6 and/or SMARCAD1 with viral genomes, we assessed the intracellular localization of these proteins during mock, Ad5 WT, and AdΔE4 infections using immunofluorescence (IF) microscopy." (PMID 34463575, 2021). "During Ad5 WT infection, depletion of SMARCAD1, SMC5, or SMC6 is associated with 2- to 3-fold, statistically significant increases in PFU at 24 hpi compared to control siRNA treatment." (PMID 34463575, 2021). "Depletion of SMARCAD1 or SMC5 is associated with statistically significant increases in the number of viral genomes at 48 hpi in Ad5 WT infection compared to control siRNA treatment." (PMID 34463575, 2021). "In this study, our objective was to investigate the specific role of Smarcad1 in the silencing of MLV upon ESC infection." (PMID 38468276, 2024). "ChIP‒qPCR performed two days after infection (2 d.a.i) showed eminent enrichment of Smarcad1 in some MLV regions: PBS, TIS, and coding regions." (PMID 38468276, 2024). "To further decipher how Smarcad1 depletion disrupts retroviral repression, we first applied ChIP using a Trim28 antibody to WT and Smarcad1 KD cells 2 and 7 days after infection." (PMID 38468276, 2024). "In contrast, during AdΔE4 infection, the SMARCAD1 protein exhibits striking reorganization to colocalize with DBP and BrdU at VRCs." (PMID 34463575, 2021). "SMARCAD1 exhibits diffuse nuclear localization in uninfected cells and remains broadly nucleoplasmic, during Ad5 WT infection." (PMID 34463575, 2021). "During AdΔE4 infection, depletion of SMARCAD1 is associated with no change in number of viral genomes, while depletion of either SMC5 or SMC6 is associated with statistically significant increases in viral genomes at 48 hpi compared to control siRNA treatment." (PMID 34463575, 2021). "During AdΔE4 infection, depletion of SMARCAD1, SMC5, or SMC6 is associated with no change in PFU at 24 hpi but is associated with 2- to 4-fold, statistically significant increases in PFU at 48 hpi compared to control siRNA treatment." (PMID 34463575, 2021). "Since SMARCAD1 is differentially enriched on viral genomes in the absence of E4 gene products and appears to show inhibitory impacts in WT infection, we expected that depletion in the context of AdΔE4 infection would also result in increased number of viral genomes." (PMID 34463575, 2021). "Depletion of SMARCAD1 may not have been sufficient to overcome the deficiencies in counteracting host defenses that occur during AdΔE4 infection." (PMID 34463575, 2021). "To test the potential inhibitory impact of SMARCAD1 and SMC6 proteins on Ad5 infection, we used small interfering RNA (siRNA) to deplete them individually prior to infection." (PMID 34463575, 2021). "Infection and integration efficiency were not affected by Smarcad1 depletion, as there was no change in the number of integrated genomic proviral copies." (PMID 38468276, 2024). "During Ad5 WT or AdΔE4 infection, Ad5 hexon, penton, and fiber proteins show no meaningful change in abundance in the context of depletion of SMARCAD1, SMC5, or SMC6 compared to control siRNA treatment." (PMID 34463575, 2021). "The data assessing the impact of depletion of SMARCAD1, SMC5, or SMC6 on Ad5 infection suggest that these proteins exert inhibitory effects on productive Ad5 infection, which are more pronounced during AdΔE4 infection." (PMID 34463575, 2021). "However, seven days after infection, Trim28 enrichment increased significantly in WT ESCs but not in Smarcad1 KD cells." (PMID 38468276, 2024). "However, accumulation of H3.3 is observed seven days after infection, is highly depends on Smarcad1 and reduced to none in the depleted cells." (PMID 38468276, 2024).
infection (continued). "Although the observed impacts of individual depletion of SMARCAD1, SMC5, or SMC6 were modest, this could be explained by redundancy within the host response since each of these proteins is part of families in which multiple members may be acting in a coordinated manner to inhibit infection." (PMID 34463575, 2021). "The iPOND and IF data suggest that SMARCAD1 and SMC6 localize to viral genomes, at VRCs, during infection with AdΔE4 but not with Ad5 WT virus." (PMID 34463575, 2021). "The immunoblotting data suggest that SMARCAD1 and SMC6 localizations at AdΔE4 viral replication centers are not driven by increased abundance during AdΔE4 infection." (PMID 34463575, 2021).
tumor (4 papers, 2018 to 2023). "If indeed conserved, then this raises the question of whether it might be possible to inhibit the growth of hamartin/tuberin deficient tumor cells by recapitulating the phenotypic effects of SMARCAD1 or PPP2R4 loss of function." (PMID 29343513, 2018). "A nonsignificant difference was found in the expression level of ARID3B and SMARCAD1 between the tumor and control tissues (p > 0.05)." (PMID 35488374, 2022).
skeletal dysplasia (1 paper, 2020). Any Mendelian diseases that affects growth and development of the skeleton. "A full non-conditional knockout (KO) of Smarcad1 using an exon-trap strategy indicated that while Smarcad1 was not essential for development, its absence caused impaired postnatal viability, reduced fertility, and skeletal dysplasia." (PMID 32160911, 2020).
SMARCAD1 also shares sentences with these, for which no sentence is quoted: Adermatoglyphia (1 paper); astroblastoma (1); bacteremia (1); Cirrhosis (1); colorectal cancer (1); cutaneous squamous cell carcinoma (1); diabetes (1); ectodermal dysplasia (1); liver disease (1); Obesity (1); Parkinson disease (1); sarcoma (1); systemic sclerosis (1); triple-negative breast carcinoma (1).